MYOF (myoferlin)
Description:
Calcium/phospholipid-binding protein that plays a role in the plasmalemma repair mechanism of endothelial cells that permits rapid resealing of membranes disrupted by mechanical stress. Involved in endocytic recycling. Implicated in VEGF signal transduction by regulating the levels of the receptor KDR (By similarity).
Synonyms: FER1L3; KIAA1207; HAE7
Tractability: Antibody: its Gene Ontology location is reachable by antibodies, with high confidence; UniProt places it where antibodies can reach, with medium confidence; UniProt predicts a signal peptide or a membrane-spanning region; the Human Protein Atlas places it where antibodies can reach. PROTAC: ubiquitination databases record sites on it; its protein half-life has been measured; a small molecule that binds it is known.
Gene: Protein-coding gene on chromosome 10 (93,306,429 to 93,482,334, reverse strand). Ensembl gene ENSG00000138119.
Subcellular location: Cell membrane; Nucleus membrane; Cytoplasmic vesicle membrane; Late endosome membrane
Subcellular location (Human Protein Atlas): Centriolar satellite; Plasma membrane; Vesicles; Basal body; Primary cilium; Primary cilium tip
Gene Ontology:
Molecular function: phospholipid binding; protein binding; calcium ion binding
Biological process: blood circulation; muscle contraction; plasma membrane repair; regulation of neurotransmitter secretion
Cellular component: cytoplasmic vesicle; cytoplasmic vesicle membrane; extracellular exosome; late endosome membrane; nuclear membrane; plasma membrane; caveola; nuclear envelope; synaptic vesicle membrane; membrane
Genetic constraint (gnomAD): Loss-of-function variants: 217 observed, 256.95 expected, observed/expected ratio (o/e) 0.84, 90% interval 0.75 to 0.94. The upper end of that interval is the gene's LOEUF score, 0.94, which puts it in group 4 of 6, group 1 being the genes least tolerant of losing a copy. Missense variants: 2,344 observed, 2,491.1 expected, observed/expected ratio (o/e) 0.94, 90% interval 0.91 to 0.97. Synonymous variants: 856 observed, 907.91 expected, observed/expected ratio (o/e) 0.94, 90% interval 0.89 to 1.
Homologues: Orthologues: chimpanzee MYOF (99% identical), macaque MYOF (99% identical), dog MYOF (95% identical), rabbit MYOF (95% identical), pig MYOF (94% identical), mouse Myof (94% identical), rat Myof (94% identical), guinea pig MYOF (91% identical), tropical clawed frog myof (76% identical), zebrafish myof (66% identical), zebrafish myofl (63% identical), Drosophila melanogaster mfr (21% identical). Paralogues in human: DYSF (57% identical), FER1L5 (41% identical), OTOF (31% identical), FER1L6 (30% identical).
Diseases named in the same sentence as MYOF in open-access papers:
MYOF is named in the same sentence as 93 diseases in open-access papers, as found by Europe PMC text mining. Sharing a sentence is not in itself a finding about the gene and the disease. The quoted sentences say what the papers report.
breast carcinoma (29 papers, 2012 to 2025). "Previous studies have shown that MYOF is strongly associated with tumour metastasis and aggressiveness in breast cancer, clear cell renal cell carcinoma, and pancreatic ductal adenocarcinoma." (PMID 39934162, 2025). "While Myoferlin plays an important role in the degradation of epidermal growth factor receptor (EGFR) in breast cancer, loss of this gene activity leads to a change in cell motility, i.e., reduced velocity of cell migration." (PMID 35330493, 2022). "Overexpression of MYOF has been associated with many cancers in humans, including breast cancer, lung cancer, and pancreatic cancer, and is shown to promote tumorigenesis, tumor cell motility, proliferation, migration, and metastasis." (PMID 32575783, 2020). "Overexpression of MYOF is associated with poor prognosis in patients with breast cancer, lung cancer, and pancreas cancer." (PMID 31828126, 2019). "Together, these data suggested that a high MYOF level is associated with increased aggressiveness of breast cancer." (PMID 30213946, 2018). "We first demonstrated that lentivirus-driven shRNA-induced MYOF loss in MDA-MB-231 breast cancer cells (MDA-231MYOF-KD) leads to an epithelial morphology compared to the mesenchymal morphology observed in control (MDA- 231LTVC) and wild-type cells." (PMID 24586247, 2014). "In contrast to our findings in pancreatic CAFs, authors showed that SMAD2/3 phosphorylation was unaffected upon myoferlin silencing but revealed an impact of myoferlin on TGFß secretion and autocrine signaling in breast cancer cell lines." (PMID 41062852, 2025). "Myoferlin inhibitor WJ460 is a small molecule that was first discovered for its anti-metastatic potential in breast cancer." (PMID 41062852, 2025). "Myoferlin has been shown to influence mitochondrial respiration and network in pancreatic and breast cancers." (PMID 38368370, 2024). "Myoferlin has been found to enhance the invasiveness of breast cancer, melanoma, and pancreatic cancer." (PMID 36147922, 2022). "MYOF dysfunction has been found in breast cancer, pancreatic adenocarcinoma, hepatocellular carcinoma, melanoma, oropharyngeal squamous cell carcinoma, head and neck squamous cell carcinoma, clear cell renal cell carcinoma, endometrioid carcinoma, and so on." (PMID 34957301, 2021). "In our previous study, we have identified that a small molecule compound (named WJ460) prevents breast cancer metastasis by targeting MYOF‐C2D domain." (PMID 33634965, 2021). "Previous evidence revealed that overexpression of MYOF is positively correlated with the poor survival rates of patients with breast cancer, pancreatic cancer, and colon cancer." (PMID 33634965, 2021). "Moreover, loss of MYOF or pharmacological inhibition of MYOF reduces breast cancer metastasis in an experimental mouse model, which demonstrated that targeting MYOF may be a promising therapeutic strategy in MYOF-driven breast cancer." (PMID 34178975, 2021). "Consistent with a previous study in breast cancer cells and Clear-Cell Renal-Cell Carcinoma, MYOF knockdown markedly in vitro inhibit cell proliferation, migration and invasion." (PMID 34178975, 2021). "Our previous investigation found that WJ460 sequesters MYOF from Rab7‐positive late endosome, thereby inhibiting the biological activity of endosomal system in breast cancer cells." (PMID 33634965, 2021). "Researchers observed that myoferlin protein is essential for the proliferation of breast cancer and pancreatic ductal adenocarcinoma (PDAC) cells." (PMID 31475450, 2019). "Not until recently, a small molecule, WJ460, which targets and pharmacologically inhibits MYOF has been found to reduce breast cancer extravasation into the lung in an animal model." (PMID 31477752, 2019). "MYOF has been intensively studied in breast cancer, which is one of the most common cancers worldwide and represents the leading cause of cancer related female death." (PMID 31828126, 2019).
breast carcinoma (continued). "While we were preparing this manuscript, a study reported a small molecule targeting myoferlin with significant antitumour effect on breast cancer and on several other cancer cell types, including pancreas cancer, prostate cancer, and ovarian cancer." (PMID 30850580, 2019). "In human breast cancer cells, MYOF regulates cell-matrix adhesion by affecting the strength of focal adhesion, structure that plays a crucial role in cell migration and matrix degradation." (PMID 31828126, 2019). "Western blotting results also confirm the elevated expression of E‐cadherin and the reduction in Vimentin and Twist1 expression, which is similar to the effect of MYOF in breast cancer cells." (PMID 29164766, 2018). "To further explore the potential role of MYOF in breast cancer tumorigenesis, we analyzed the baseline MYOF expression in 90 human breast cancer biopsy samples and 10 adjacent non-transformed specimens." (PMID 30213946, 2018). "In an EGF-induced EMT model, MYOF ablation impairs the ability of breast cancer cells to undergo EMT." (PMID 30213946, 2018). "Our results indicated that MYOF expression in breast cancer samples was much higher than in normal tissues." (PMID 30213946, 2018). "Our findings demonstrate that WJ460 blocks breast cancer metastasis through directly targeting MYOF." (PMID 30213946, 2018). "In parallel, loss of MYOF or pharmacological inhibition of MYOF by WJ460 reduces breast cancer extravasation into the lung parenchyma in an experimental metastasis mouse model, which reveals an essential role of MYOF in breast cancer progression." (PMID 30213946, 2018). "Depletion of myoferlin in the human breast cancer cell line MDA-MB-231 (MDA-231MYOFKD) reduced migration and invasion and caused the cells to revert to an epithelial phenotype." (PMID 29721195, 2018). "In recent years, several groups of researchers have described the selective overexpression of myoferlin (MYOF) in breast carcinoma specimens." (PMID 30213946, 2018). "Here they show the druggability of myoferlin with a small molecule inhibitor in breast cancer and demonstrate its anti-breast cancer effects in vitro and in vivo." (PMID 30213946, 2018). "This was done by using an anti-myoferlin immunogold labelling of purified exosomes from MDA-MB-231 breast cancer cells." (PMID 27845903, 2016). "Over-synthesis of MYOF in breast cancer cell lines leads to an increased invasion phenotype and secretion of matrix metalloproteinases (MMPs), while silencing of the gene restores the normal phenotype, possibly by blocking the EGFR signaling pathway." (PMID 25945082, 2015). "To investigate how MYOF-depletion influences the adhesion properties of breast cancer cells, we measured cell spreading and substrate attachment in 2D cultures using a novel cell adhesion bioassay developed in our laboratory." (PMID 24586247, 2014). "Previous work by our group demonstrated a pleiotropic role for MYOF in regulating human breast cancer cell shape, motility and invasion in vitro." (PMID 24586247, 2014). "During early studies, we discovered a positive correlation between MYOF expression and invasive phenotype in several well-characterized breast cancer cell lines." (PMID 24586247, 2014). "MYOF (myoferlin) depletion in breast cancer cells has shown to promote mesenchymal to epithelial transformation and stall invasion with potential as a biomarker or drug target for metastatic cancer diagnosis and therapy." (PMID 24894543, 2014). "We previously discovered that myoferlin (MYOF) is overexpressed in breast cancer cells and depletion of MYOF results in a mesenchymal to epithelial transition (MET) and reduced invasion through extracellular matrix (ECM)." (PMID 24586247, 2014). "In congruence, higher MYOF protein expression was observed by immunoblotting in the highly-invasive breast cancer cell lines relative to those with low invasive potential." (PMID 22761893, 2012).
breast carcinoma (continued). "We selected the MDA-MB-231 cells for these experiments since they exhibited high levels of MYOF protein expression in our survey, and were previously shown to have the greatest invasive capacity compared to a large panel of breast cancer cell lines." (PMID 22761893, 2012). "In a separate study, MYOF was found to be 1 of 39 genes selectively over-expressed in breast carcinoma using 20 human breast cancer cases." (PMID 22761893, 2012). "Mining of transcriptome and proteome databases from breast cancer cell lines revealed higher levels of MYOF mRNA and protein in the more invasive lines compared with poorly invasive breast tumor cells or normal mammary epithelial cells (i.e., MCF-10A)." (PMID 22761893, 2012). "We recently reported on the mathematical modeling of the role of MYOF in breast cancer cell invasion." (PMID 22761893, 2012). "For example, in one microarray study, MYOF was 1 of 39 genes found to be over-represented in breast carcinoma." (PMID 22761893, 2012). "In this study, using an in vitro human breast cancer cell model, we demonstrate that myoferlin is abundantly expressed in invasive breast tumor cells." (PMID 22761893, 2012). "Published microarray datasets using breast cancer cell lines also support greater MYOF expression in the invasive basal B group compared with the luminal subtype." (PMID 22761893, 2012). "Microarray and proteomic studies in the cancer literature have reported MYOF expression in breast cancer specimens and relevant cell lines." (PMID 22761893, 2012). "To correlate the expression of MYOF with the invasive capacity of breast cancer cells, we analyzed five mammary cell lines: MCF-10A, MCF-7, T47D, BT549, and MBA-MB-231." (PMID 22761893, 2012). "However, a link between myoferlin and TGFß signaling has been described previously in breast cancer cells." (PMID 41062852, 2025). "Indeed, previous studies demonstrated that MYOF depletion reduced tumor development in a xenograft model of human breast cancer." (PMID 34178975, 2021). "EGFR has been identified to be regulated by MYOF in breast cancer." (PMID 34957301, 2021). "Interestingly, myoferlin was previously reported to regulate the TGF-β autocrine loop in breast cancer cells, and Smad2, a downstream transducer, was recently reported as a mitofusin interactor in mitochondrial fusion." (PMID 32575867, 2020). "Interestingly, an elegant mathematical model predicts the role of myoferlin in the metastatic spreading of breast cancer." (PMID 31248212, 2019). "In breast cancer cell lines, MYOF forms a complex with EGFR to induce EGFR recycling." (PMID 31477752, 2019). "MYOF expression showed a positive correlation with breast cancer progression." (PMID 30213946, 2018). "Collectively, our results demonstrated that WJ460 can serve as a first lead compound for the development of MYOF-targeted therapeutic agents and targeting MYOF by WJ460 may be a promising therapeutic strategy in MYOF-driven breast cancer." (PMID 30213946, 2018). "Using a combination of mathematical modeling and in vitro invasion assays, researchers uncovered that MYOF might act as a critical mediator in breast cancer metastasis." (PMID 30213946, 2018). "Genetic ablation of MYOF promotes a mesenchymal–epithelial transition in breast cancer cells." (PMID 30213946, 2018). "Given its exosome-related function, MYOF may act as a candidate protein for EV-modulated tumor growth and spread in breast cancer and small molecule compounds targeting MYOF (e.g., WJ460) seem likely to play an important role in EV-dependent tumor progression." (PMID 30213946, 2018). "Recent studies have shown that the expression of MYOF is up‐regulated in several types of cancers, such as breast cancer, lung cancer, pancreatic adenocarcinoma and oropharyngeal squamous cell carcinoma, and high expression of MYOF is associated with poor outcome in those patients." (PMID 29164766, 2018). "MYOF is a regulator of breast cancer invasion as well as RTK recycling." (PMID 30213946, 2018).
breast carcinoma (continued). "In this work, we examined whether MYOF-depleted MDA-MB-231 breast cancer cells would exhibit altered TGF-β receptor signaling and be refractory to undergoing an EMT in response to the growth factor." (PMID 29721195, 2018). "MYOF plays a pivotal role in breast cancer invasion and metastasis." (PMID 30213946, 2018). "That MYOF plays a pleiotropic role in breast cancer cell migration and invasion, and that these data have now been translated to an animal model of human cancer offers the potential to use MYOF as a biomarker of disease progression, invasion and impending metastasis." (PMID 24586247, 2014). "Given a possible association between MYOF expression and invasive potential, we examined whether MYOF contributed to breast cancer cell invasion." (PMID 22761893, 2012). "Recently, increasing studies have revealed that MYOF is overexpressed in many kinds of human cancers, including pancreas cancer, ovarian carcinoma, prostate cancer, breast cancer and renal cell cancer, indicating that this protein may have important roles in tumorigenesis and malignant progression." (PMID 31828126, 2019). "In addition, research has revealed that MYOF functions in breast cancer invasion and epithelial-to-mesenchymal transition (EMT), suggesting that MYOF may act as a modifier of breast cancer metastasis." (PMID 30213946, 2018). "Based on these observations, coupled with the observation that MYOF expression was increased in breast cancer specimens and breast cancer cell lines with high invasive potential, we hypothesized that MYOF depletion would impair the motility of breast cancer cells." (PMID 22761893, 2012). "Myoferlin silencing impaired the 2D and 3D in vitro migration ability of PDAC cell lines as previously suggested in breast cancer." (PMID 31248212, 2019). "Either MKL1/2 or SRF depletion decreases MYOF level and triggers EGFR phosphorylation similar to that in breast cancer cells." (PMID 31828126, 2019). "Further study indicated that MYOF acts as a key regulator in EGFR degradation after its activation and internalization in breast cancer cells." (PMID 30213946, 2018). "Further studies reveal that MYOF mainly contributes to metastasis via enhancing the expression of MMP‐2 and regulating EMT in breast cancer cells." (PMID 29164766, 2018). "We recently discovered that silencing a protein involved in membrane dynamics, myoferlin (MYOF), in the highly invasive MDA-MB-231 breast cancer cell line induces MET and modulates the invasive capacity of these cells." (PMID 24586247, 2014). "For instance, a high level of LIMS1 promoted tumor progression in breast cancer, and the LIMS1–myoferlin signaling axis may contribute to this process." (PMID 36901953, 2023). "The identification of myoferlin as a key regulator of EGFR (Epidermal Growth Factor Receptor) activity through inhibition of non-clathrin endocytosis in breast cancer cells was important in understanding the molecular mechanisms involved in cancer growth." (PMID 37538852, 2023). "We then selected four non-breast cancer cell lines (SW1990 pancreatic cancer cells, 143B sarcoma cells, A549 lung cancer cells, and SKOV3 ovarian cancer cells) representing other human tumor types with high MYOF levels." (PMID 30213946, 2018). "MYOF may act as a key regulator in epidermal growth factor receptor (EGFR) degradation after its activation and internalization in breast cancer cells." (PMID 30213946, 2018). "MYOF depletion induced the increased size of FAs and elevated the phosphorylation of FAKY397, an activation site of FAK correlates with the FAs assembly, which is consistent with previous results in breast cancer cells." (PMID 29164766, 2018). "Our work demonstrated that WJ460 blocked breast cancer invasion and reversed highly metastatic mesenchymal-like breast cancer cells back to an epithelial state, suggesting that WJ460/MYOF complex formation may impede the role of MYOF in invasion." (PMID 30213946, 2018).